S100A7 (S100 calcium binding protein A7)
Diseases named in the same sentence as S100A7 in open-access papers (continued):
Sharing a sentence is not in itself a finding about the gene and the disease.
dementia (1 paper, 2009). Loss of intellectual abilities interfering with an individual's social and occupational functions. "Control immunoadsorption studies using MS-SELDI technology confirmed the SELDI-MS evidence and demonstrated that S100A7 content is elevated in the CSF of moderate AD dementia cases (CDR2) relative to the normal controls." (PMID 19159013, 2009). "We sought to understand how S100A7 may influence AD clinical dementia, and found that S100A7 may selectively attenuate AD amyloid neuropathology through promotion of the “non-amyloidogenic” α-secretase processing of APP." (PMID 19159013, 2009). "Since S100A7 expression is regulated in the AD brain as a function of clinical dementia as well as amyloid-plaque neuropathology, we hypothesized that S100A7 might play an important role in amyloidogenesis eventually influencing cognitive functions." (PMID 19159013, 2009). "Based on the evidence that S100A7 protein species in CSF might be an AD biomarker, we continued to explore the expression of S100A7 in the AD brain and tested the hypothesis that S100A7 expression may be regulated as a function of clinical dementia or neuropathology." (PMID 19159013, 2009).
dental caries (1 paper, 2021). The decay of a tooth, in which it becomes softened, discolored, and/or porous. "S100A7 is a calcium- and zinc-binding protein with a prominent role in regulating the immune response and antimicrobial humoral response, and has also been associated with dental caries." (PMID 34287355, 2021).
dysplasia (1 paper, 2010). A usually neoplastic transformation of the cell, associated with altered architectural tissue patterns. "In another independent study using iTRAQ, we also reported increased expression of S100A7 protein in oral premalignant lesions (dysplasia), albeit in only limited number of cases." (PMID 20689826, 2010). "Further, increased nuclear accumulation of S100A7 in HNSCC as compared to dysplastic lesions warrants a large-scale longitudinal study of patients with dysplasia to evaluate its potential as a determinant of increased risk of transformation of oral premalignant lesions." (PMID 20689826, 2010). "Furthermore, increased nuclear accumulation of S100A7 in HNSCC as compared to dysplastic lesions warrants a large-scale longitudinal study of patients with dysplasia to evaluate its potential as a determinant of increased risk of transformation of oral premalignant lesions and recurrence in HNSCC." (PMID 20689826, 2010).
endothelial dysfunction (1 paper, 2020). In vascular diseases, endothelial dysfunction is a systemic pathological state of the endothelium (the inner lining of blood vessels) and can be broadly defined as an imbalance between vasodilating and vasoconstricting substances produced by (or acting on) the endothelium. "Proinflammatory cytokines from such inflamed fat also stimulates S100A7 and DEfB4A expression and can cause endothelial dysfunction in local blood vessels in part due to inadequate endothelin-1 action." (PMID 32826922, 2020).
hepatocellular carcinoma (1 paper, 2022). A malignant tumor that arises from hepatocytes. "Meanwhile, a low expression of S100A7 was connected to a poor prognosis of hepatocellular carcinoma." (PMID 35205150, 2022).
Hyperkeratosis (1 paper, 2025). Hyperkeratosis is a histopathological term defining a thickened stratum corneum and may be present in many different skin conditions, with many possible overlaps. "Supplementation of the STAT3 overexpressing model with activated or naïve T cells, did not significantly increase S100A7 levels, however, activated T cells in contrast to naïve T cells induced strong parakeratosis and hyperkeratosis, both hallmarks of psoriatic skin." (PMID 40678130, 2025).
invasive ductal breast carcinoma (1 paper, 2017). The most common type of invasive breast carcinoma, accounting for approximately 70% of breast carcinomas. "We then investigated clinical or biological roles of S100A7 expression among 150 Japanese patients with invasive ductal breast carcinoma by immunohistochemistry." (PMID 28629450, 2017).
mesothelioma (1 paper, 2022). A usually malignant and aggressive neoplasm of the mesothelium which is often associated with exposure to asbestos. "A high level of S100A7 was significantly correlated to a poor prognosis of overall survival (OS) for BLCA and mesothelioma (MESO) within the TCGA project." (PMID 35205150, 2022).
neck cancer (1 paper, 2024). "S100A7 is upregulated in breast, bladder, lung, head, and neck cancer tissues." (PMID 38473906, 2024).
Neisseria gonorrhoeae infection (1 paper, 2023). "A recent study of Neisseria gonorrhoeae infection revealed that human but not murine S100A7 could be used to evade host nutritional immunity." (PMID 37769710, 2023).
non-small cell lung carcinoma (1 paper, 2021). A group of at least three distinct histological types of lung cancer, including non-small cell squamous cell carcinoma, adenocarcinoma, and large cell carcinoma. "S100A7 plays an important roles in the development of estrogen receptor-positive breast carcinoma and non-small cell lung cancer." (PMID 34122500, 2021).
ocular infection (1 paper, 2017). "IL-8 and S100A7, amongst other factors induced by Th17 cells, are chemotactic for neutrophils, an influx of which is associated with C. trachomatis infection and contributes to pathology in animal models of urogenital and ocular infection." (PMID 28966918, 2017).
oral cavity cancer (1 paper, 2024). A primary or metastatic malignant neoplasm involving the oral cavity. "Analyzing tissue specimens from 93 patients with oral cavity cancer and 87 samples from normal oral mucosa found that S100A7 was significantly upregulated in cancerous samples." (PMID 38473906, 2024).
oral disorders (1 paper, 2019). "High S100A7 expression is observed in potentially malignant oral disorders and is associated with the risk of malignant transformation in oral dysplasia." (PMID 31208114, 2019).
psoriasis vulgaris (1 paper, 2022). Plaque psoriasis is the most common presentation of psoriasis. "In addition, S100A7 overexpression in the plaques of patients with psoriasis vulgaris with joint inflammation compared with psoriasis vulgaris was demonstrated." (PMID 36235175, 2022).
pterygium (1 paper, 2023). A wedge-shaped fibrovascular lesion arising from the bulbar conjunctiva and extending to the cornea. "Compared with primary pterygium tissue, S100A7 expression was increased in recurrent pterygium tissue and MAPK inflammatory response pathway was activated." (PMID 36768371, 2023).
renal carcinoma (1 paper, 2010). A carcinoma arising from the epithelium of the renal parenchyma or the renal pelvis. "Interactions with RanBPM have recently been shown to promote migration of renal cancer cells, suggesting the potential for S100A7 to influence invasive potential of cancer cells." (PMID 20689826, 2010).
tracheal tumor (1 paper, 2011). "mRNA extracted from human tracheal tumor tissue which was amplified by RT-PCR to provide the region coding for the S100A7 gene." (PMID 22082027, 2011).
tuberous sclerosis complex (1 paper, 2022). "It has been shown that the overexpression of S100A7 is correlated with the overexpression of MLH1, a DNA mismatch repair protein in tuberous sclerosis complex patients." (PMID 35205150, 2022).
upper respiratory tract infections (1 paper, 2012). "In line with this, it is tempting to speculate that ASIT-treated patients, who have regained a normal S100A7 production, in turn have a reduced propensity to develop upper respiratory tract infections compared to their untreated counterparts." (PMID 22230654, 2012).
urticaria (1 paper, 2025). A vascular reaction of the skin characterized by erythema and wheal formation due to localized increase of vascular permeability. "S100A7, S100A8, S100A9, S100A12, IL6 and SOCS3, whose mRNA expression correlated positively with the urticaria activity score and may have a potential diagnostic value." (PMID 40635160, 2025).
viral infection (1 paper, 2022). "As S100A7 and other members of the S100 family signal through RAGE45, we next explored whether RAGE inhibitors can be used to suppress host inflammatory responses during viral infection in alveolus chips when administered the drugs in a therapeutic mode (2 hours after infection)." (PMID 35396513, 2022).
viral pneumonia (1 paper, 2022). Inflammation of the lung parenchyma that is caused by a viral infection. "Nevertheless, our data suggest that TRPV4 inhibitors may represent an attractive therapy for viral pneumonia as they may both suppress viral load via DDX3X signaling and dampen the associated inflammatory response via the S100A7/RAGE pathway." (PMID 35396513, 2022).
tumor (84 papers, 2005 to 2026). "Under pathological conditions, increased intracellular expression of S100A7 was linked to enhanced tumor cell proliferation and migration." (PMID 38217031, 2024). "Subsequently, we explored the relationship between S100A7 expression and immune characteristics, methylation, tumor heterogeneity, tumor stemness, and gene mutations." (PMID 38499391, 2024). "Overexpression of S100A7 induced mammary glandhyperplasia and recruited tumor-associated macrophages, and this study highlighted anovel role of LPS in driving S100A7 expression." (PMID 39037373, 2024). "In non-tumor environments, S100A7 is reported to be positively associated with the infiltration of CD8+ T-cells and the suppression of human fibroblast proliferation." (PMID 35205150, 2022). "In particular, our results have elucidated how the overexpression of S100A7 induces hyperplasia in the mammary gland and recruits tumor‐associated macrophages in the S100A7‐overexpressing bitransgenic mouse model." (PMID 33969603, 2022). "It has been shown that activation of S100A7-regulated pathways is linked to increased cancer-associated angiogenesis, the promotion of M2 macrophage infiltration in the tumor microenvironment and enhancement of tumorsphere growth." (PMID 35205150, 2022). "Initially, 93 proteins were found, and up to 30 overexpressed were selected, and CD44, S100A7, and S100P were significantly associated as putative candidates for the early phase of tumor progression." (PMID 36412636, 2022). "Under abnormal conditions, S100A7, located in the extracellular compartment, can cause the movement of immune cells and tumor cells." (PMID 33912559, 2021). "Under pathological conditions, elevated intracellular S100A7 expression is associated with enhanced proliferation and metastasis of tumor cells." (PMID 34323409, 2021). "S100A7 is an EF-hand calcium-binding protein that has been suggested to be implicated in cell proliferation, migration, invasion and tumor metastasis." (PMID 28212564, 2017). "In particular, it is reported that S100A1 and S100A7 are linked to tumor growth, while S100A4 and S100A8 are linked to metastasis." (PMID 28615627, 2017). "Statistical analysis showed that S100A7 expression was associated with tumor grade (P <0.01) and lymph node metastasis (P <0.05)." (PMID 28212564, 2017). "Furthermore, the potential association between S100A7 level and tumor mutational burden (TMB)/microsatellite instability (MSI) was analyzed across all TCGA cancers." (PMID 35205150, 2022). "In addition, CD163+ tumor associated-macrophages were positively associated with S100A7 and cPLA2 expression in malignant breast cancer patients." (PMID 35135586, 2022). "S100A7 is associated with increased macrophage infiltration during tumor development." (PMID 33912559, 2021). "In addition to promoting cancer cell progression, S100A7 promotes tumor‐associated macrophage infiltration and angiogenesis, thus supporting the development of the tumor microenvironment." (PMID 34323409, 2021). "Furthermore, S100A7 could facilitate the secretion of immunomodulators, including IL-6, in tumors and tumor-associated immune cells, thereby enhancing tumor infiltration." (PMID 38499391, 2024). "In addition, exocrine S100A7 could promote M2 macrophage infiltration and polarization by up‐regulating M2 macrophage associated proteins, and tumor angiogenesis by enhancing the activation of p‐ErK and p‐FAK pathways." (PMID 34323409, 2021). "Previous studies have shown that S100A7 plays a crucial role in tumor growth and metastasis in ER-negative breast cancer cells by activating of extracellular signal-regulated kinase and nuclear factor kappa-light-chain-enhancer of activated B cells signaling." (PMID 40900789, 2025). "For example, upregulation of genes (e.g. CHI3L1, S100A7, and MAL) is associated with poor prognosis, increases aggressiveness, and tumor microenvironment modulation." (PMID 40802546, 2025).
tumor (continued). "Spearman’s and Wilcoxon’s tests were used to investigate the relationships between S100A7 expression and immune characteristics, methylation, tumor heterogeneity, and tumor stemness." (PMID 38499391, 2024). "Of all proteins, only S100A7 demonstrated a statistically significant trend regarding tumor staging and staining intensity." (PMID 38892279, 2024). "Our staining results of 190 samples show that expression of GLI1, GLI3, KRT16, and S100A7 was mostly detected in the epidermal layer overlying or bordering the tumor mass." (PMID 38892279, 2024). "This study elucidated the relationship between S100A7 expression and tumor stemness, tumor heterogeneity, methylation, and chemotherapy sensitivity." (PMID 38499391, 2024). "We suggest further examination of KRT16 and S100A7, especially since S100A7 showed a statistically significant trend regarding tumor staging and staining intensity." (PMID 38892279, 2024). "Despite its high expression in the early stages of OSCC, S100A7 inhibits OSCC tumor growth, invasion, and progression." (PMID 38473906, 2024). "Due to tumor heterogeneity, the effect of S100A7 on immunomodulators, immune activity and infiltration varies across in different tumor types." (PMID 38499391, 2024). "LPS has beenassociated with S100A7 expression and tumor progression, while metabolites likecadaverine and TMAO exhibit complex interactions with cancer cells and tumormicroenvironments, influencing cellular behavior and tumor growth." (PMID 39037373, 2024). "We show that staining of GLI1, KRT16, and S100A7 appears in the same places in the samples (same samples and different tumor slices) in all stages, while the localization of staining of GLI3 differs from the other proteins at lower stages." (PMID 38892279, 2024). "In ER positive breast cancers S100A7 correlated with worse prognosis parameters and higher tumor grade." (PMID 39830522, 2024). "RAGE/S100A7 interactions conditions the tumor microenvironment by increasing the recruitment of MMP9-positive TAMs." (PMID 39830522, 2024). "The tumor stemness indicators RNAss, ENHss, DMPss, DNAss, EREG-METHss, and EREG-EXPss were also associated with S100A7 expression." (PMID 38499391, 2024). "S100A7 and S100A9 also contribute to oxidative stress, recruitment of tumor-associated macrophages (TAMs), and pro-angiogenic signaling." (PMID 39830522, 2024). "We then explored the crucial biomarkers of MRS1-tumor cells, finding that S100A7, S100A8, and PTTG1 were up-regulated in the MRS1 phenotype both in bulk data (TCGA-BLCA and GSE13057) and single-cell data." (PMID 37543645, 2023). "Seven hub genes, REG4, S100A7, CLCA1, FABP4, RETNLB, SFRP2, and WNT10A, were all significantly associated with CC patient prognosis and differentially expressed in normal and tumor tissues." (PMID 36941538, 2023). "The metabolic subtype with S100A7 high expression recognizes the immuno-suppressive tumor microenvironment and predicts well therapeutic response of immunotherapy in BLCA." (PMID 37543645, 2023). "We used siRNA to knockdown S100A7 expression, and the results showed that S100A7 knockdown significantly inhibited tumor cells proliferation." (PMID 37543645, 2023). "Prominently, we observed that S100A7 is mostly expressed on the MRS1-tumor cells, and can predict the clinical outcomes of BLCA patients." (PMID 37543645, 2023). "Pharmacological inhibition of cPLA2 suppressed S100A7-mediated tumor growth and metastasis in multiple pre-clinical models including transgenic and humanized patient-derived xenograft (PDX) mouse models." (PMID 35135586, 2022). "For example, infiltration and polarization of M2-Møs are promoted by tumor-derived S100A7, which can directly promote tumor proliferation and migration via intracellular binding to JAB1 and paracrine interaction with RAGE receptors." (PMID 36211375, 2022).